APOE (apolipoprotein E)
Diseases named in the same sentence as APOE in open-access papers (continued):
Sharing a sentence is not in itself a finding about the gene and the disease.
amyloid (continued). "In vivo amyloid stage was significantly associated with ApoE-ε4 status, such that the percentage of ApoE-ε4 carriers increased with increasing amyloid stage (chi-squared (χ2) test, p = 0.001)." (PMID 30704537, 2019). "Our findings are consistent with previous studies where APOE-TR mice were crossed to various models of amyloidosis and recapitulate (at least in part) the allele-dependent effect of APOE on amyloid deposition found in humans." (PMID 31623648, 2019). "Lipid-free apolipoproteins related to apoE are implicated with several amyloidosis as a result of their proneness to misfold." (PMID 31071995, 2019). "ApoE ε4 has been linked to an increase Aβ accumulation, aggregation and deposition in the brain and for instance, this allele is associated with enhanced amyloid pathology even in cognitively normal people." (PMID 29510495, 2018). "Especially because of the triple association observed between coherence (and RPDC), amyloid deposition, and ApoE ε4 status, one can ask if the changes in those EEG bands are the consequence of elevated amyloid deposition." (PMID 29081745, 2017). "Again, the pattern of results largely recapitulated the CSF biomarker results, including strong associations between amyloid groups and APOE genotypes." (PMID 29190651, 2017). "ApoE deficient (ApoE−/−) mice represent a model for AD induced by metabolic dysfunction in addition to amyloidosis." (PMID 27824104, 2016). "In summary, these basic and clinic researches support that ApoE ɛ 4 is highly associated with amyloid pathology in the brain." (PMID 27891223, 2016). "The non-APOE amyloid GRSwas also associated with postmortem neuropathologic β-amyloid andneurofibrillary tangle burden and in an independent sample was associatedwith plasma p-tau181 concentrations (a robust indicator ofcerebral amyloidosis)." (PMID 40703204, 2025). "This suggests that carrying an APOE ε4 allele may exacerbate the gut microbial changes associated with amyloid accumulation." (PMID 41037094, 2025). "Furthermore, the APOE ε4 allele, which impairs Aβ clearance and accelerates its aggregation, is a major genetic risk factor for amyloid plaque deposition." (PMID 40807232, 2025). "In addition, female mouse microglia show increased expression of an APOE-driven network of genes associated with aging, amyloidosis, and tau protein aggregation." (PMID 36831738, 2023). "Furthermore, the disease-gene associations related to amyloidosis (Apolipoprotein E [APOE], C3, FGA, Transthyretin [TTR], and Serum amyloid P-component [APCS or SAMP]) showed significant enrichment (FDR = 2.66E-5)." (PMID 37875373, 2023). "In addition, APOE ε4 allele plays a role as a modulator of the relationship between plasm Aβ and amyloid plaque in the brain." (PMID 35453600, 2022). "Our results suggest that genes in the axonal branching and synaptic maintenance, along with APOE, may be implicated in the downstream consequences of amyloidosis." (PMID 35425899, 2022). "In addition to the known association, we have identified novel variants in the APOE region that affect amyloidosis." (PMID 30361487, 2021). "Changes in plasma APOE, miR-107, and miR-650 levels may be a marker of neurodegeneration during AD associated with amyloid metabolism and cell cycle disorders." (PMID 32973449, 2020). "ApoE ε4 allele has differential effects on the Aβ burden depending on the existing amyloidosis and may enhance vulnerability to progressive tau accumulation in the AD spectrum independent of Aβ." (PMID 33129364, 2020).
amyloid (continued). "Further, intraperitoneal administration of an anti-apoE antibody into AD mice improves cognitive function and reduces brain Aβ load, and decreasing APOE expression by antisense oligonucleotides significantly alleviates Aβ pathology in amyloid mice homozygous for the APOE3 or APOE4 allele." (PMID 32366277, 2020). "In the model herein presented, expression changes in ApoE may be caused by the aging process itself and by the presence of abnormal tau and acute amyloid pathology characteristic of the model." (PMID 31596896, 2019). "For instance, impaired cerebral metabolism could compromise the ability of microglia to remove amyloid deposition and might underlie the observed earlier and faster rate of amyloid accumulation in APOE-ε4 homozygotes." (PMID 29793545, 2018). "In contrast to PART and HS, there is some evidence of an association between arteriolosclerosis and APOE in the presence of amyloidosis, and some evidence of an inverse association between APOE ε2 and markers of cerebrovascular disease relative to what is observed in AD." (PMID 29190651, 2017). "Indeed, all except 1 of the 10 patients with MND, MND + FTD and FTD, collectively, who showed both amyloid and tau in their brains were over 65 years of age at death, and of these 9 patients, 6 were bearers of APOE ε4 allele." (PMID 27036121, 2016). "The results on the real data showed that both GOSC-SCCA and KG-SCCA could find an important association between the APOE SNPs and the amyloid burden measure in the frontal region of the brain." (PMID 27585988, 2016). "Hence, patients with MND, MND + FTD and FTD most likely to show amyloid in their brains were those who died after the age of 65 years and bore APOE ε4 allele." (PMID 27036121, 2016). "Therefore, we conclude that APOE is an important mediator of amyloid pathology in the earliest stages of AD-associated clinical decline." (PMID 23554593, 2013). "Presence of the apoE ε4 allele may also be associated with amyloid deposition in the blood vessels, which could be associated withCAA and WMH pathology." (PMID 23762308, 2013). "After a f/u of 3 years (with adjustment for age, sex, APOE ε4 status), higher adherence to the Mediterranean diet was associated with a decrease in amyloid load (β = −0.01, p = 0.007), suggesting a protective effect of the Mediterranean diet against future amyloid plaque accumulation." (PMID 41154306, 2025). "In the evaluation of MCI, it is therefore important to map APOE-4 status, but in clinical practice, knowledge of APOE status usually contributes less to the diagnostic assessment than mapping cognitive function, brain imaging, and mapping markers of amyloid deposition and neuronal damage." (PMID 41368162, 2025). "In summary, we hypothesise that amyloidosis might be a common pathophysiological process underlying the neurological disorders of CM and AD, most likely initiated by parasite-induced co-upregulation of APOE and APP in the cerebral tissues." (PMID 39023792, 2025). "In addition, the PrecivityADTM test for plasma LC-MS/MS assays of Aβ quantification and qualitative APOE isoform-specific prototyping was completed in the first phase of the Plasma test for Amyloid Risk Screening study for clinical use to evaluate individuals experiencing early cognitive impairment." (PMID 35453600, 2022). "Though additional studies are needed, the present results suggest that axonal guidance and synaptic pruning genes, along with APOE, may modulate the association between amyloid pathology and downstream neurodegeneration, providing exciting targets for future mechanistic studies." (PMID 35425899, 2022). "The findings from this study support the hypothesis that in the general population of older adults, the association of APOE with tau accumulation would appear to be amyloid-dependent and at minimum may be substantially weaker than its association with amyloidosis." (PMID 33426524, 2020).
amyloid (continued). "Therefore, in the context of the amyloid cascade hypothesis, APOE acts prior to amyloid deposition and the remaining genetic risk factors identified through GWASs act between amyloid deposition and clinical onset of AD." (PMID 31199530, 2019). "However, APOE allele status and sex may be associated with differences in AD-type pathophysiology that are downstream of amyloid and more proximal to clinical symptoms." (PMID 31642932, 2019). "In addition, in the presence of abundant amyloidosis, APOE ɛ4 may be associated with accelerated entorhinal cortex tau deposition." (PMID 31642932, 2019). "Amyloidosis, has been recently demonstrated differently tuned by the different APOE-alleles in AD and in cognitively normal older adults and the two hypotheses might share more than expected also in other neurodegenerative diseases with mutual causative interactions." (PMID 29518107, 2018). "For example, greater amyloid burden was found to explain faster FA decline in parahippocampal cingulum, body corpus callosum, and forceps minor in healthy older adults, and those carrying the APOE-ε4 risk allele may also preferentially benefit from PA." (PMID 28360853, 2017). "In addition to increased brain amyloid load, apoE4 KI mice have reduced levels of CNS apoE and it has been postulated that the overall lower levels of apoE protein may explain the increased amyloid load and risk for AD in apoE4 carriers." (PMID 21034469, 2010). "Instead, they suggest that in APOE‐ε4 carriers the timing of amyloidosis is more genetically preordained than the timing of disease advancement." (PMID 40018326, 2025). "Other studies have demonstrated that deleting one copy of human APOE ε4 or APOE ε3 significantly reduces APOE levels and amyloid pathology in mouse models." (PMID 41384508, 2025). "APOE e4 plays a dual role in promoting both amyloid pathology and cerebrovascular dysfunction, with significant implications for CSVD." (PMID 40376151, 2025). "For instance, a homozygous carrier of the APOE ε3 Christchurch variant developed MCI nearly three decades later than expected, despite AD‐causative PSEN1 carriership and presence of amyloidosis." (PMID 40613482, 2025). "APOE e4 carriers exhibit increased amyloid deposition, which impairs clearance mechanisms reliant on perivascular arteriolar pulsations." (PMID 40376151, 2025). "Decreasing apoE expression was suggested as a therapy since APOE deletion reduces Aβ deposition in amyloid mouse models and rescues neurodegeneration in tauopathy mouse models." (PMID 40275327, 2025). "Further, we demonstrated that amyloid-induced atrophy is exacerbated in women and with APOE-ε4 carriership." (PMID 41270680, 2025). "When brain sections containing Aβ plaques from amyloid model mice were cultured with adult mouse astrocytes, the astrocytes internalized and degraded Aβ in a manner dependent on both ApoE and LRP1." (PMID 39944166, 2025). "We also wanted to assess at which stage of the amyloid plaque development ApoE steps in the process." (PMID 39435610, 2025). "Unlipidated aggregated ApoE has been shown to promote a pro-inflammatory response and to seed amyloid plaque formation in mice." (PMID 40770764, 2025). "APOE ε4 frequencies in patients with other amyloid-forming diseases are comparable to those in healthy controls, despite the consistent presence of APOE within amyloid plaques across these conditions." (PMID 40943807, 2025). "Previous evidence suggests that the interaction between wild-type ApoE and amyloid-beta (Aβ) regulates both Aβ aggregation and clearance, thereby directly influencing amyloid plaque formation and plays a key role in AD pathogenesis." (PMID 40892789, 2025). "KUNV affected physiological, behavioral, cognitive, amyloid pathology, viral load, and immune measures in middle aged NL-G-F mice in an apoE isoform-dependent fashion." (PMID 40599380, 2025).
amyloid (continued). "Collectively, these findings strongly speak for the key role of ApoE in modulating the microglia capable of amyloid plaque compaction." (PMID 39435610, 2025). "In summary, the data of the current study show that exposure to the KUNV strain of WNV affects physiological, behavioral, cognitive, amyloid pathology, viral load, and immune measures in middle-aged NL-G-F mice in an apoE isoform-dependent fashion." (PMID 40599380, 2025). "Both 5XFAD lines have been crossed with human APOE knock-in mice (APOE2, APOE3, and APOE4) to generate EFAD mice for the study of APOE genotype in amyloidosis." (PMID 40361247, 2025). "In contrast, ApoE knockout mice showed significant reductions in amyloid deposits and plaques in a model of amyloidosis." (PMID 41516203, 2025). "Further, it indicates for the first time that the impact of APOE‐ε4 is dose‐dependent such that homozygosity predicts steeper progression of amyloid accrual over the same range of PPO values." (PMID 40018326, 2025). "The data of the current study show that exposure to WNV affects physiological, behavioral, cognitive, amyloid pathology, viral load, and immune measures in middle aged NL-G-F mice in an apoE isoform-dependent fashion." (PMID 40599380, 2025). "Repetitive injection of apoE-antibodies was shown to decrease Aβ plaque deposition and insoluble Aβ accumulation in the cortex and hippocampus in an amyloid mouse model of AD." (PMID 40275327, 2025). "Kinetic studies should help to understand how precisely different APOE genotypes modulate these different aspects of amyloid plaque biology." (PMID 39528861, 2024). "In this study, we demonstrate for the first time that the deletion of mir‐33 in an amyloidosis mouse model significantly increases ABCA1 protein levels, increases apoE lipidation, and reduces the levels of insoluble Aβ peptides and amyloid plaque deposition." (PMID 39345217, 2024). "Intensities of ApoE-positive signals in the amyloid plaques and levels of ApoE and α1-antichymotrypsin in the soluble fraction were significantly elevated by the Mme deficiency in the 24-mo-old APP-Tg mice." (PMID 39348937, 2024). "We demonstrated that deletion of mir‐33 significantly increased ABCA1 protein levels, increased the lipidation of apoE, and reduced amyloid pathology and gliosis at 8 months of age." (PMID 39345217, 2024). "We demonstrated that isogenic iPSC-derived in vitro BBB models successfully captured aspects of AD-related amyloid pathologies by illustrating the effects of different APOE isoforms on Aβ trafficking and deposition." (PMID 39394110, 2024). "According to our results, in amyloid and p-tau–positive individuals, the use of PACC as the primary outcome is appropriate; however, in amyloid-positive individuals and amyloid-positive APOE ε4 carriers, a single neuropsychological test was more sensitive." (PMID 38165338, 2024). "It has been demonstrated that the liver tropism, for example in the case of Onpattro, approved in 2018 for the treatment of hereditary transthyretin-mediated amyloidosis (hATTR amyloidosis) by siRNA, is based on the endogenous targeting mediated by ApoE." (PMID 38587758, 2024). "The APOE ε4 not only increases cerebral amyloid pathology, neuroinflammation and tau pathology, but also potentiates the impact of amyloid pathology on tau pathology." (PMID 39080778, 2024). "By elucidating the amyloidogenic properties of ApoE, the present study provides a new perspective on the role of ApoE in the pathogenesis of amyloidosis, as well as contributing to our understanding the pathogenesis of cholesterol granuloma in leopard geckos." (PMID 38877049, 2024). "APOE‐npscore and amyloid status were strongly related to p‐tau217 trajectories, whereas potential confounding factors of BMI and estimated kidney function and LIBRA index were not." (PMID 38970274, 2024).
amyloid (continued). "These mouse models can then be crossed with mouse models of amyloidosis or tauopathy to observe how various APOE isoforms affect AD-related pathological features." (PMID 38462606, 2024). "It is clear that APOE plays an important role in the interaction between these cell types, with astrocytic APOE being a major driver of the amyloid plaque pathology which in its turn modifies the microglia response." (PMID 39528861, 2024). "TREM2 can function alone or in conjunction with additional molecules, such as apolipoprotein E (APOE), to affect microglial functions in disorders caused by amyloid and tau, as well as inflammation and metabolism." (PMID 39015316, 2024). "By establishing the novel role of ApoE in amyloidosis, this study aimed to bring a fresh perspective to the comparative pathology of ApoE function and contributes to the future elucidation of the pathogenesis of cholesterol granulomas in leopard geckos." (PMID 38877049, 2024). "Deletions of TREM2 and ApoE lead to impaired microglial cell response to amyloid plaques; and ApoE4 impairs microglial response in the presence of amyloid." (PMID 39695808, 2024). "We provide evidence that microglia lacking endogenous APOE expression, can be stirred in their response to amyloid pathology by APOE secreted by astrocytes." (PMID 39528861, 2024). "This has major implications on disease, as APOE has such varied functions, from lipid transportation to amyloid clearance and microglial responses to amyloid and tau." (PMID 38139206, 2023). "Our results show that deletion of P2X4 increases microglial ApoE, reduces sAß and reverses cognitive deficits, further supporting a minimal role of microglial ApoE in amyloid plaque formation but a potential protective function toward synapse integrity." (PMID 37145189, 2023). "The function and toxicity of ApoE and amyloid proteins like Aβa tau and α-synuclein can be also influenced by their interactions in amyloidoses." (PMID 36817952, 2023). "ApoE is likely to function in many of these processes, participating not only in amyloid clearance and plaque seeding directly but also in the acquisition of microglial phenotypes that facilitate or inhibit amyloid production and clearance." (PMID 38139206, 2023). "It has been proposed that males and females share genetic regulators of amyloidosis, but, as amyloid pathology progresses, it has been demonstrated that APOE exerts sex-specific effects on gene expression, resulting in sex bias in disease manifestation." (PMID 38139206, 2023). "In conclusion, our survey suggests that in sporadic YOAD amyloid deposition and APOE ɛ4 interact and are fundamental in its pathogenesis." (PMID 37090959, 2023). "The lipid metabolism cluster contained APOE, which is genetically associated to AD, and APP, the precursor that produces the peptides found in amyloid plaques." (PMID 38104170, 2023). "To examine how these endothelial gene expression changes relate to AD neuropathology, we performed linear regression analysis of individual gene expression on histologic amyloid plaque burden, phosphorylated tau content, and APOE genotype." (PMID 37208174, 2023). "In fact, a CSF proteomic study in the APPPS1 mouse model of amyloidosis highlighted increased levels of proteins related to glial activation and identified APOE and SERPINA3 as CSF biomarkers." (PMID 37303123, 2023). "These parameters, amyloid 42/40 ratio, age and ApoE genotype are incorporated into an Amyloid Probability Score (APS)–a score that identifies low, intermediate or high risk of having a PET scan positive for cerebral amyloid." (PMID 35208878, 2022). "Herein, we characterized the impact that ApoE has on amyloid pathology in a FDD transgenic mouse model, a model of cerebral ADan amyloidosis." (PMID 36436561, 2022).